EIF2A (eukaryotic translation initiation factor 2A)
Description:
Functions in the early steps of protein synthesis of a small number of specific mRNAs. Acts by directing the binding of methionyl-tRNAi to 40S ribosomal subunits. In contrast to the eIF-2 complex, it binds methionyl-tRNAi to 40S subunits in a codon-dependent manner, whereas the eIF-2 complex binds methionyl-tRNAi to 40S subunits in a GTP-dependent manner.
Synonyms: eIF-2A; CDA02; MSTP004; MSTP089; MST089
Tractability: PROTAC: ubiquitination databases record sites on it; its protein half-life has been measured.
Gene: Protein-coding gene on chromosome 3 (150,546,678 to 150,586,016, forward strand). Ensembl gene ENSG00000144895.
Subcellular location (Human Protein Atlas): Cytosol
Gene Ontology:
Molecular function: cadherin binding; protein binding; ribosome binding; translation initiation factor activity; tRNA binding
Biological process: regulation of translation; ribosome assembly; translational initiation; response to amino acid starvation; translation
Cellular component: blood microparticle; cytoplasm; eukaryotic translation initiation factor 2 complex; extracellular region
Genetic constraint (gnomAD): Loss-of-function variants: 52 observed, 59.2 expected, observed/expected ratio (o/e) 0.88, 90% interval 0.7 to 1.11. The upper end of that interval is the gene's LOEUF score, 1.11, which puts it in group 4 of 6, group 1 being the genes least tolerant of losing a copy. Missense variants: 598 observed, 629.01 expected, observed/expected ratio (o/e) 0.95, 90% interval 0.89 to 1.02. Synonymous variants: 204 observed, 226.84 expected, observed/expected ratio (o/e) 0.9, 90% interval 0.8 to 1.01.
Homologues: Orthologues: chimpanzee EIF2A (98% identical), macaque EIF2A (97% identical), dog EIF2A (96% identical), rabbit EIF2A (95% identical), mouse Eif2a (93% identical), rat Eif2a (92% identical), pig EIF2A (91% identical), guinea pig EIF2A (87% identical), tropical clawed frog eif2a (75% identical), zebrafish eif2a (69% identical), Drosophila melanogaster eIF2A (40% identical), Caenorhabditis elegans eif-2A (36% identical).
Diseases named in the same sentence as EIF2A in open-access papers:
EIF2A is named in the same sentence as 77 diseases in open-access papers, as found by Europe PMC text mining. Sharing a sentence is not in itself a finding about the gene and the disease. The quoted sentences say what the papers report.
viral infection (14 papers, 2018 to 2025). "It is well known that ERS and PKR are two major pathways that regulate eIF2a during virus infection, and p-eIF2α inhibits global protein translation and thereby reduces protein folding load during ERS." (PMID 40145089, 2025). "The stark response to viral infection shown in the transcriptional increase of factors such as Ifitm2, Irf7, Stat1, and Eif2a, among others, indicates a heart actively mounting a host response to the invading SARS-CoV-2." (PMID 37081485, 2023). "PKR plays a protective role during viral infection: it is activated by double-stranded viral RNA, which leads to the phosphorylation of eIF2A and an inhibition of the synthesis of viral proteins." (PMID 35232816, 2022). "In a viral infection, host cells phosphorylate the eukaryotic initiation factor 2A (eIF2a) by protein kinase R (PKR) to inactivate translation." (PMID 33275611, 2020). "In summary, interferon translation occurs in wild type cells in the presence of SG, at a time when eIF2a is phosphorylated and translation factors had been sequestered into SG during virus infection." (PMID 31905741, 2019). "Our study suggests the very provocative possibility that enteroviruses may also exploit the eIF2A/eIF2D-dependent mechanism to survive under conditions in which the cell is actively attempting to thwart viral infection by inhibiting normal translation." (PMID 36689548, 2023). "eIF2A or eIF2D can be used to replace eIF2 in the expression of these mRNAs or initiate non-AUG codon translation under stressful conditions due to viral infection." (PMID 32703221, 2020). "It has been suggested that, upon viral infection, translation can be switched from the standard 5 ́cap dependent mechanism to one using non-AUG codons facilitated by eIF2A and/or eIF2D." (PMID 38023930, 2023).
breast cancer (7 papers, 2019 to 2025). A primary or metastatic malignant neoplasm involving the breast. "The EIF2A locus is amplified in patients with lung and head and neck squamous cell carcinoma (SCC) as well as esophageal carcinoma, and elevated eIF2A levels have been associated with poor prognosis in breast cancer." (PMID 40749049, 2025). "Furthermore, eIF2A promotes breast cancer cell survival during paclitaxel-mediated integrated stress response and stimulates translation of CCNB1 mRNA leading to hepatocellular carcinoma progression." (PMID 40749049, 2025). "The current study suggests that targeting the EIF2A‐mediated translation in combination with paclitaxel may present a potential new strategy for breast cancer treatment." (PMID 31211507, 2019). "Collectively, our findings reveal a novel mechanism for paclitaxel resistance and suggest that targeting EIF2A combined with ISR agonist may be a potential treatment regimen to overcome drug resistance for breast cancer." (PMID 31211507, 2019). "In lung and breast cancer animal models, citrate treatments inhibited tumor growth by suppressing the insulin-like growth factor type 1 receptor (IGF-1R)/AKT/PTEN/eukaryotic translation initiation factor 2A (eIF2A) pathway." (PMID 35884416, 2022). "Moreover, patients with breast cancer exhibited higher ISR after chemotherapy, and the elevated mRNA levels of HMOX1, SHMT2 and EIF2A were correlated with poor prognosis." (PMID 31211507, 2019). "Moreover, eIF2A is not prognostic for CRC, breast cancer or lung cancer in TCGA and CRC in our dataset (K.S. and K.A., unpublished data)." (PMID 31175057, 2019).
melanoma (6 papers, 2021 to 2025). A malignant, usually aggressive tumor composed of atypical, neoplastic melanocytes. "Together, these results indicate that eIF2A promotes tumoral traits in metastatic melanoma cells independently of proliferation and that dependency on eIF2A is acquired upon oncogenic transformation." (PMID 40749049, 2025). "In a previous screen, we had found eIF2A as a factor potentially involved in melanoma metastatic progression." (PMID 40749049, 2025). "To obtain insights into the role of eIF2A in melanoma progression, we tested the effect of eIF2A depletion on the tumorigenic properties of a panel of melanoma cell lines." (PMID 40749049, 2025). "ALDH18A1 affects proline metabolism and thus regulates protein synthesis through GCN2 and eIF2a and thereby melanoma cell proliferation." (PMID 39051546, 2024). "The centrosomal localization of Nav1.5 may be related to the promotion of cell proliferation, or it may indicate a role of Nav1.5 in regulating cell migration, as has recently been demonstrated with the centrosomal localization of eIF2A in melanoma cells." (PMID 41516295, 2025). "As with thapsigargin, WX8 induced PERK‐dependent phosphorylation of EIF2A protein and upregulation of ATF4 and DDIT3 proteins in melanoma A375 cells accompanied by translocation of transcription factors ATF4 and CEBPb to the nucleus." (PMID 38414326, 2024). "Both drugs inhibited thapsigargin induced PERK‐dependent phosphorylation of EIF2A and expression of ATF4 in melanoma A375 cells." (PMID 38414326, 2024). "In melanoma, p‐PERK and eIF2a levels are the critical initiators of ER stress and are significantly increased by treatment with melatonin." (PMID 34185414, 2021). "Here, we explore the functions of eIF2A during oncogenic transformation using a melanoma cell model consisting of the nontumoral melanocytic cell line Mel-ST and its metastatic counterpart Mel-STR obtained by H-RasG12V overexpression." (PMID 40749049, 2025). "Using a melanoma cell model consisting of nontumoral melanocytic Mel-ST cells and their metastatic counterpart obtained by H-Ras transformation, we unexpectedly find minimal effects of eIF2A depletion on translation." (PMID 40749049, 2025).
lung carcinoma (4 papers, 2015 to 2022). "Moreover, benzyl isothiocyanate causes autophagy in lung cancer A549 cells through EIF2AK3 and EIF2A pathways, and preliminary treatment with the ER stress suppressor 4-PBA attenuates the autophagy induction." (PMID 36497321, 2022).
squamous cell carcinoma (4 papers, 2020 to 2025). A carcinoma arising from squamous epithelial cells. "In contrast, in squamous cell carcinoma, inhibition of EIF2S1 is compensated for by an alternative translation initiation factor, EIF2A, thereby sustaining the survival of squamous cell carcinoma despite the inhibition of EIF2S1." (PMID 40365898, 2025). "Silencing of eIF2A led to a substantial decrease in tumor formation in mice engrafted with Eif2a-null squamous cell carcinomas (SCCs), and reintroduction of eIF2A into these cell lines, rescued tumor formation." (PMID 32192132, 2020). "Recently, it was shown that eIF2A promotes the translation of non‐AUG uORFs in squamous cell carcinomas (SCC), positively regulating their downstream oncogenic ORFs by modulating the scanning mechanism of the ribosome or altering the fidelity of start codon recognition." (PMID 39417309, 2025).
hepatocellular carcinoma (3 papers, 2014 to 2023). A malignant tumor that arises from hepatocytes. "WDR4 interacts with EIF2A to promote the translation of CCNB1, thereby promoting the proliferation, metastasis and sorafenib resistance of hepatocellular carcinoma cells." (PMID 37783676, 2023). "In hepatocellular carcinoma, WDR4 interacts with the translation initiation factor EIF2A to promote the translation of CCNB1 and thus promote proliferation, metastasis and sorafenib resistance." (PMID 37783676, 2023). "Our present findings in human cells clearly demonstrate that neither eIF2A nor eIF2D are involved in protein synthesis directed by HCV IRES, and are in accord with a recent result demonstrating that knockdown of eIF2A or eIF2D in hepatoma cells has little effect on HCV IRES-driven translation." (PMID 29487587, 2018).
osteosarcoma (3 papers, 2012 to 2025). A usually aggressive malignant bone-forming mesenchymal neoplasm, predominantly affecting adolescents and young adults. "After treated with a chemical library in osteosarcoma U2OS cells, higher levels of p-eIF2a, calreticulin (CALR), and HMGB1 were detected in U2OS cells treated with Paclitaxel/Docetaxel than in U2OS cells treated with Fluorouracil/Capecitabine." (PMID 36605427, 2022).
renal fibrosis (3 papers, 2019 to 2024). A final common manifestation of a wide variety of chronic kidney diseases characterized by glomerulosclerosis and tubulointerstitial fibrosis. "During this progress, elevated ER stress and cytoplasmic Ca2+ overload, both of which were evoked by the ROS-triggered Bip/eIF2a/CHOP signaling pathway, play critical roles in BV-induced renal fibrosis." (PMID 35873571, 2022).
chronic lymphocytic leukaemia (2 papers, 2014 to 2019). "Elevated mRNA translation is a key driver of carcinogenesis and PEITC has been recently shown to increase eIF2a phosphorylation and inhibit mTORC1 activity resulting in inhibition of translation in MCF-7 cells and in B cells from chronic lymphocytic leukaemia." (PMID 30066177, 2019).
colon carcinoma (2 papers, 2012 to 2020). "In colon cancer, hypoxia induces PERK-dependent phosphorylation of eukaryotic translation initiation factor 2a (eIF2a) and translation of ATF4." (PMID 33050301, 2020).
glioma (2 papers, 2023). A benign or malignant brain and spinal cord tumor that arises from glial cells (astrocytes, oligodendrocytes, ependymal cells). "We observed the elevated eIF2a phosphorylation and increased XBP1 levels, both markers of ER stress, in S4-treated glioma cells." (PMID 37386564, 2023).
heart failure (2 papers, 2020 to 2022). Inability of the heart to pump blood at an adequate rate to meet tissue metabolic requirements. "In a model of canine microembolism of the left anterior descending coronary artery, the resultant heart failure was associated with increased calreticulin and other markers of injurious ER stress including eIF2a phosphorylation (George, Sabbah, Xu, Wang, & Wang, 2011)." (PMID 32323496, 2020). "Comparing the phosphorylated levels of eIF2a and PERK in patients with heart failure to controls, a considerable activation of the PERK to the eIF2a arm of the stress response was discovered." (PMID 36703744, 2022).
Hepatic steatosis (2 papers, 2015 to 2023). Steatosis is a term used to denote lipid accumulation within hepatocytes. "Our observation of the down-regulated expression of p-JNK, PERK and p-eIF2a in Tpl2 knockout mice with the decreased hepatic steatosis supported the involvement of ER stress in TPL2/JNK mediated steatosis." (PMID 26560698, 2015). "Moreover, PERK/eIF2a is required for the expression of lipogenic genes and progression of hepatic steatosis." (PMID 36830016, 2023).
leukemia (2 papers, 2015 to 2022). A malignant (clonal) hematologic disorder, involving hematopoietic stem cells and characterized by the presence of primitive or atypical myeloid or lymphoid cells in the bone marrow and the blood. "In patient-derived T-ALL xenografts (PD T-ALL) the drug induced cell death and activated AMPK as well as EIF2A phosphorylation, demonstrating that this molecular event is not limited to cell line models but is also present in primary leukemia cells." (PMID 26542945, 2015). "In contrast, CD treatment inhibited eIF2a activation and suppressed ATF4 and JAG1 up-regulation induced by leukemia SEVs." (PMID 35401837, 2022). "We show that FK866 induces a translational arrest in leukemia cells through inhibition of MTOR/4EBP1 signaling and of the initiation factors EIF4E and EIF2A." (PMID 26542945, 2015). "PERK inhibition decreased p-eIF2a and JAG1 up-regulation in BMECs co-cultured with leukemia cells." (PMID 35401837, 2022). "To investigate if the adhesion between leukemia cells and ECs induces EC UPR response and PERK activation, we blocked the ligands of ICAM-1 and VCAM-1 and found that PERK, eIF2a, and JAG1 activation was modestly attenuated by blocking LFA-1 but largely unaffected by blocking VLA-4." (PMID 35401837, 2022).
metabolic syndrome (2 papers, 2023 to 2024). A cluster of metabolic risk factors for CARDIOVASCULAR DISEASES and TYPE 2 DIABETES MELLITUS. "eIF2A KO mice developed a metabolic syndrome and had decreased life spans by one year of age, suggesting eIF2A may have a role in aging." (PMID 37602404, 2023).
non-small cell lung carcinoma (2 papers, 2011 to 2015). A group of at least three distinct histological types of lung cancer, including non-small cell squamous cell carcinoma, adenocarcinoma, and large cell carcinoma. "The phosphorylation of EIF2A as well as the activation of eukaryotic translation initiation factor 2-alpha kinase 2 (EIF2AK2, best known as PKR) have been associated with favorable disease outcome in a cohort of 193 non-small cell lung carcinoma (NSCLC) patients." (PMID 26300886, 2015).
Parkinson disease (2 papers, 2023 to 2024). A progressive degenerative disorder of the central nervous system characterized by loss of dopamine producing neurons in the substantia nigra and the presence of Lewy bodies in the substantia nigra and locus coeruleus. "It was suggested that LPS significantly increased DUSP2 expression but caused a decrease in the p-eIF2a/eIF2a ratio, which was reversed by salubrinal in the LPS-induced intraneural hemi-Parkinson disease (PD) model." (PMID 37208441, 2023).
ZIKV infection (2 papers, 2021). "Selective inhibition of eIF2a dephosphorylation using salubrinal protects ZIKV infection-induced first trimester-derived trophoblast apoptosis." (PMID 33500388, 2021). "ZIKV infection upregulated GADD34 expression, implying that de-phosphorylation of EIF2A is promoted in ZIKV-infected cells." (PMID 34452345, 2021). "Interestingly, ZIKV infection did not inhibit EIF2A-independent SG formation." (PMID 34452345, 2021).
Alzheimer disease (1 paper, 2022). A progressive, neurodegenerative disease characterized by loss of function and death of nerve cells in several areas of the brain leading to loss of cognitive function such as memory and language. "For instance, in an Alzheimer’s disease (AD) mouse model, GCN2 deletion reduced phosphorylated eIF2a (p-eIF2a) levels and improved spatial memory while in a different model, GCN2 deletion seems to be deleterious." (PMID 35887167, 2022).
aneurysm (1 paper, 2025). Bulging or ballooning in an area of an artery secondary to arterial wall weakening. "Taken together, these findings suggest that activation of the PERK/EIF2A/ATF/CHOP pathway contributes to AAA development, and inhibition abrogates aneurysm formation by decreasing VSMC apoptosis." (PMID 39846252, 2025).
atherosclerosis (1 paper, 2015). A disease characterized by the build-up of fatty material and calcium deposition in the arterial wall resulting in partial or complete occlusion of the arterial lumen. "This suggests that the exacerbation of the UPR, which is dependent on EIF2A, can be thought as a relevant strategy to potentiate the effect of FK866 in conditions in which activation of the EIF2A-dependent UPR is desirable, i.e., diabetes, atherosclerosis, or neurodegenerative disorders." (PMID 26542945, 2015).
cholestasis (1 paper, 2017). Impairment of the bile flow caused by obstruction within the liver, or outside the liver in the bile duct system. "In order to investigate the effect of cholestasis on HBsAg-associated ER stress, activation of GRP78, PERK, eIF2a, and Chop was analyzed by Western blotting." (PMID 28881751, 2017).
colorectal cancer (1 paper, 2012). A primary or metastatic malignant neoplasm that affects the colon or rectum. "We next sought to dissect the mechanisms by which natural variation in 3′-end usage impacted gene expression, using as case studies IRF5 and DIP2B, which lie in genomic regions associated with susceptibility to lupus and colorectal cancer, respectively, as well as NAB1 and EIF2A." (PMID 22916029, 2012).
Dystonia (1 paper, 2018). An abnormally increased muscular tone that causes fixed abnormal postures. "Therefore, given the previous evidence suggesting a role of eIF2a signaling dysregulation in dystonia, and our own RNA-seq data, we investigated UPR genes and proteins to assay the baseline status of the UPR in Thap1 recombinant mice." (PMID 29364887, 2018).
epileptic seizures (1 paper, 2024). "Since eIF2a and eIF4B phosphorylation positively regulate BACE1 mRNA levels and PERK-mediated phosphorylation of eIF2a is induced in TLE, epileptic seizures might increase BACE1 mRNA levels via eIF2a phosphorylation." (PMID 39545066, 2024).
head and neck cancer (1 paper, 2021). A primary or metastatic malignant neoplasm affecting the head and neck. "It is of interest, then, that increased expression of PKR (eIF2AK2), a kinase that phosphorylates eIF2α, and of eIF2A, the recruiter of alternate tRNAi, occur in a majority of head and neck cancers (TCGA dataset) and that they significantly correlate with poor survival of HNSCC patients." (PMID 35048066, 2021).
histiocytic sarcoma (1 paper, 2016). An aggressive malignant neoplasm with a poor response to therapy, usually presenting as stage III/IV disease. "The other three patients exhibit an expansion of clones harbouring del(8p) with additional driver mutations (EP300, MLL2 and EIF2A), with one patient developing trans-differentiation into CD19-negative histiocytic sarcoma." (PMID 27199251, 2016).
infertile (1 paper, 2025). "The same study found that insertion of a different, piggyback transposon into the second intron resulted in viable, but infertile males due to failed sperm individualization, supporting the idea of cell-type specific function of eIF2A." (PMID 40600802, 2025).
influenza infection (1 paper, 2016). "Previous studies demonstrated inhibition of eIF2a phosphorylation during influenza infection and it was proposed that this inhibition is mediated by the activation of the cellular inhibitor of PKR, P58-IPK." (PMID 27525483, 2016).